FMO3 (flavin containing dimethylaniline monoxygenase 3)
Diseases named in the same sentence as FMO3 in open-access papers (continued):
Sharing a sentence is not in itself a finding about the gene and the disease.
Hyperinsulinemia (1 paper, 2015). An increased concentration of insulin in the blood. "Blocking the effects of hyperinsulinemia in ob/ob mice by knocking down the insulin receptor further induced FMO3 protein, consistent with the notion that the signaling pathways utilized by insulin to suppress Fmo3 become partially resistant to insulin in ob/ob mice." (PMID 25849138, 2015).
interstitial lung disease (1 paper, 2024). A diverse group of lung diseases that affect the lung parenchyma. "Expression of FMO3 is significantly up-regulated in both explanted skin fibroblasts, and in skin biopsies, from patients with SSc Moreover, in a recent study, SSc patients with interstitial lung disease (ILD) and esophageal dysmotility had higher plasma TMAO levels than non-SSc controls." (PMID 39180015, 2024).
ovarian endometriosis (1 paper, 2023). A non-neoplastic disorder characterized by the growth of endometrial tissue in the ovaries. "In our previous study, we estimated that approximately 60% of ovarian endometriosis may be originated from the tubal epithelia based on the FMO3 and DMBT1 expression study." (PMID 36936232, 2023).
preeclampsia (1 paper, 2025). Preeclampsia is a hypertensive disorder of pregnancy that is characterized by new-onset hypertension with proteinuria presenting after 20 weeks of gestation, and depending on mild or severe forms may initially present with severe headache, visual disturbances, and hyperreflexia. "Knockdown of FMO3 has a significant alleviating effect on preeclampsia-like symptoms." (PMID 41459234, 2025).
cancer (6 papers, 2016 to 2023). A tumor composed of atypical neoplastic, often pleomorphic cells that invade other tissues. "One study showed that ectopic re-expression of FMO3 increased apoptosis and decreased cell viability in liver-derived cancer cell lines." (PMID 37589009, 2023). "Several publications have reported the relationships between these five ER-related genes (SPP1, KIF2C, LPCAT1, KPNA2, and FMO3) and cancers." (PMID 35915607, 2022). "FMO3 is predominately expressed in the liver where it plays a role in the metabolism of xenobiotics including a number of anti-cancer drugs." (PMID 26893359, 2016).
metabolic disease (6 papers, 2021 to 2025). A congenital disorder (due to inherited enzyme abnormality) or acquired (due to failure of a metabolically important organ) disorder resulting from an abnormal metabolic process. "Changes in FMO3 activity could be an important mechanism in metabolic diseases, and modulating FMO3 activity may represent a novel strategy for improving these metabolic disorders." (PMID 40177494, 2025). "Studies have found that the high expression of FMO3 is associated with an increase in plasma VLDL levels and the inhibition of cholesterol synthesis, which may lead to metabolic disorders." (PMID 40282416, 2025). "Although TMAO is a possible pro-inflammatory mediator, Fmo3 may play a role in metabolic diseases regardless of TMAO formation." (PMID 37958806, 2023).
tumor (4 papers, 2017 to 2023). "Six sex-specific, Esr1-dependent transcripts–A1bg, Fmo3, Cabyr, Cspg5, Mthfd1l, Tff3–are strongly implicated in hepatocarcinogenesis based on their expression, prognostic power, or oncogenic/tumor suppressive properties." (PMID 34068249, 2021). "The qRT-PCR results revealed a significant upregulation of CBX2, SPP1, and ZC4H2, alongside a notable downregulation of FMO3 in tumor tissues." (PMID 37287752, 2023). "Significant disparities in protein expression levels of CBX2, SPP1, ZC4H2, and FMO3 were detected between tumor tissues and matched para-tumor tissues." (PMID 37287752, 2023). "The results showed that tumor cells from nonmetastatic tumors expressed high levels of MMP1, KRT1, and MMP13 and low levels of MGST1, FAM133A, and FMO3." (PMID 36569924, 2022).
cardiovascular disease (3 papers, 2005 to 2023). "The combined use of inhibitors of choline TMA lyase and FMO3 could provide novel therapeutic strategies for cardiovascular disease prevention by stabilizing existing atherosclerotic plaques." (PMID 37337893, 2023).
infection (3 papers, 2019 to 2025). The state of being infected such as from the introduction of a foreign agent such as serum, vaccine, antigenic substance or organism. "Seven of 12 P450 mRNAs analysed by MANOVA (Cyp 1a2, 2c29, 2e1, 3a25, 4a10, 4a14 and 7a1) were significantly downregulated during infection as was flavin containing monooxygenase 3 (Fmo3)." (PMID 31299982, 2019). "Firstly, we checked the infection and knockdown efficiencies of FMO3-RNAi." (PMID 41459234, 2025). "They found that infection with P. gingivalis significantly increased plasma TMAO levels and affected lipid metabolism, primarily by modulating the expression of hepatic flavin-containing monooxygenase 3 (FMO3)." (PMID 40001895, 2025).
genetic disorder (2 papers, 2017 to 2024). "Furthermore, the genetic test for mutations in the FMO3 gene is not available on the National genomic test directory for rare and inherited diseases, unlike genetic tests for other inborn errors of metabolism." (PMID 38238734, 2024).
kidney disease (2 papers, 2016 to 2022). "FMO3 genotype, kidney disease progression, and mortality: During a median follow-up of 3.3 years (interquartile range, 1.9–4.6 years) the average relative decline in eGFR was 8.5% per year (standard error = 0.015) and there were a total of 45 deaths." (PMID 27513517, 2016). "Increased excretion of trimethylamine has been reported in patients with renal disease, a condition characterized by decreased activity of flavin-containing monooxygenase (EC 1.14.13.8) isoform 3 enzyme (FMO3), which induces the accumulation of trimethylamine in urine." (PMID 36557321, 2022).
FMO3 also shares sentences with these, for which no sentence is quoted: hyperlipidemia (6 papers); essential hypertension (2); liver cancer (2); allergic asthma (1); asthma (1); coronary artery diseases (1); fungal infections (1); heart failure (1); Impaired glucose tolerance (1); ischemic stroke (1); liver (1); lung adenocarcinoma (1); lung carcinoma (1); neuroblastoma (1); prostate hyperplasia (1); psychiatric disease (1); viral hepatitis (1).